HCN3 (hyperpolarization activated cyclic nucleotide gated potassium channel 3)
Description:
Hyperpolarization-activated ion channel that are permeable to sodium and potassium ions, with an about 3:1 preference for potassium ions. Contributes to the native pacemaker currents in heart (If) and in neurons (Ih). In particular, plays a pivotal role in maintaining excitability and promoting rhythmic burst firing within hypothalamic nuclei. Exerts a significant influence on the configuration of the cardiac action potential waveform. Does not appear to play a prominent role in the processing of acute, neuropathic, or inflammatory pain (By similarity).
Synonyms: KIAA1535
Tractability: Small molecule: a structure with a bound ligand is known; it belongs to a druggable protein family. Antibody: UniProt places it where antibodies can reach, with high confidence; its Gene Ontology location is reachable by antibodies, with high confidence; UniProt predicts a signal peptide or a membrane-spanning region. PROTAC: ubiquitination databases record sites on it; its protein half-life has been measured; a small molecule that binds it is known.
Target class: Ion channel; Voltage-gated ion channel; Cyclic nucleotide-regulated channel
Gene: Protein-coding gene on chromosome 1 (155,277,328 to 155,289,848, forward strand). Ensembl gene ENSG00000143630.
Subcellular location: Cell membrane
Pathways (Reactome):
Neuronal System: HCN channels
Gene Ontology:
Molecular function: protein binding; voltage-gated potassium channel activity; voltage-gated sodium channel activity; monoatomic ion channel activity; sodium channel activity
Biological process: cellular response to cAMP; potassium ion transmembrane transport; regulation of membrane depolarization; regulation of membrane potential; sodium ion transmembrane transport; potassium ion import across plasma membrane; regulation of heart rate by cardiac conduction; regulation of SA node cell action potential; sodium ion import across plasma membrane; monoatomic ion transport; potassium ion transport; transmembrane transport
Cellular component: HCN channel complex; plasma membrane; axon; dendrite; membrane
Genetic constraint (gnomAD): Loss-of-function variants: 36 observed, 58.24 expected, observed/expected ratio (o/e) 0.62, 90% interval 0.47 to 0.82. The upper end of that interval is the gene's LOEUF score, 0.82, which puts it in group 3 of 6, group 1 being the genes least tolerant of losing a copy. Missense variants: 930 observed, 1,100.9 expected, observed/expected ratio (o/e) 0.84, 90% interval 0.8 to 0.89. Synonymous variants: 425 observed, 446.19 expected, observed/expected ratio (o/e) 0.95, 90% interval 0.88 to 1.03.
Homologues: Orthologues: chimpanzee HCN3 (99% identical), macaque HCN3 (98% identical), pig HCN3 (97% identical), rabbit HCN3 (96% identical), dog HCN3 (95% identical), mouse Hcn3 (95% identical), guinea pig HCN3 (95% identical), rat Hcn3 (91% identical), Drosophila melanogaster Ih (44% identical), Drosophila melanogaster Cngl (22% identical), zebrafish kcnh6a (20% identical), zebrafish kcnh3 (18% identical), and 12 more. Paralogues in human: HCN4 (69% identical), HCN2 (60% identical), HCN1 (59% identical), KCNH2 (21% identical), KCNH7 (20% identical), KCNH4 (19% identical), KCNH6 (19% identical), CNGB1 (19% identical), CNGA3 (19% identical), KCNH3 (19% identical), KCNH1 (19% identical), KCNH5 (18% identical), and 5 more.
Diseases named in the same sentence as HCN3 in open-access papers:
HCN3 is named in the same sentence as 29 diseases in open-access papers, as found by Europe PMC text mining. Sharing a sentence is not in itself a finding about the gene and the disease. The quoted sentences say what the papers report.
breast carcinoma (3 papers, 2021 to 2025). "HCN channels, particularly HCN2 and HCN3, are overexpressed in breast cancer and associated with poor survival outcomes." (PMID 40764992, 2025). "Western blot employed to determine the expression of endogenous HCN2, HCN3, BRCA1, BRCA2, and RAD51, confirmed that either HCN2 or HCN3 was overexpressed in the breast cancer cells, whilst HEK293 had low expression in both of HCN2 and HCN3." (PMID 40764992, 2025). "Two other members of the HCN family, HCN2 and HCN3, were shown to be overexpressed in clinical breast cancer and to have adverse prognostic significance; they were also predictive markers for ivabradine response in in vitro breast cancer models." (PMID 37239316, 2023). "Overexpression of HCN2 and HCN3 proteins was consistently found in breast cancer cells, with BT474 and TNBC cells MDA‐MB‐231, MDA‐MB‐453 showing the most significant upregulation." (PMID 34841695, 2021). "We found that HCN2 and HCN3 are overexpressed in breast cancer cells compared with normal breast epithelia, and the high expression of HCN2 and HCN3 is associated with poorer survival in breast cancer patients." (PMID 34841695, 2021). "Further in vivo support of this oncogenic effect is reflected in our HCN2 and HCN3 expression in over 200 primary breast cancers which showed a significant correlation with poorer survival." (PMID 34841695, 2021). "Hence IVA can be used with PARP, specifically for breast cancers that express HCN2/HCN3 to induce synergistic effect." (PMID 40764992, 2025). "Based on our results, only HCN2 and HCN3 are overexpressed in breast cancer." (PMID 34841695, 2021). "We found both HCN2 and HCN3 were predominantly localized to the cell membrane, suggesting that HCN2 and HCN3 could be functionally important in breast cancer cells." (PMID 34841695, 2021). "In the current study, we found HCN2 and HCN3 are overexpressed in breast cancer cells." (PMID 34841695, 2021). "Since breast cancer cells showed increased expression of both HCN2 and HCN3, we investigated the significance of each to ER‐stress." (PMID 34841695, 2021). "Using immunohistochemistry to examine HCN2 and HCN3 protein expression of primary breast cancer in tissue microarray, we confirmed that HCN2 and HCN3 were significantly upregulated in tumour compared with normal breast epithelia." (PMID 34841695, 2021). "From the analysis of 316 breast cancer cases, those cases which showed both high HCN2 and HCN3 expression were most frequently of the TNBC subtype (68.4%), prompting us to focus our study on TNBC." (PMID 34841695, 2021). "IVA treatment led to significant reduction of RAD51-EGFP signals in all 5 breast cancer cell lines that overexpressed HCN2 or HCN3, but not in HEK293." (PMID 40764992, 2025). "On contrast, IVA induces ER stress in breast cancer cells with increased HCN2/HCN3 expression, which is not found in non-neoplastic cell line HEK293." (PMID 40764992, 2025).
epilepsy (3 papers, 2022 to 2026). A brain disorder characterized by episodes of abnormally increased neuronal discharge resulting in transient episodes of sensory or motor neurological dysfunction, or psychic dysfunction. "One study recruited 298 epilepsy patients, and through Sanger sequencing, three rare heterozygous variants (R457H, P630L, R661Q) in the HCN3 gene were identified." (PMID 41603014, 2026). "Although two non‐synonymous variants in HCN have been described in epilepsy patients, the role of HCN3 in epileptogenesis remains poorly understood." (PMID 39361439, 2024). "Through detailed functional assays, we aim to elucidate the potential role of HCN3 in epilepsy and provide a framework for evaluating variants in similar genes." (PMID 39361439, 2024). "This study aims to address these challenges by investigating the pathogenicity of novel HCN3 variants identified in epilepsy patients." (PMID 39361439, 2024). "We recruited a cohort of 298 epilepsy patients to screen for genetic variants in the HCN3 (NM_020897.3) using Sanger sequencing." (PMID 39361439, 2024). "Here, we identified three novel HCN3 variants, R457H, P630L and R661Q, through targeted genetic screening of 298 epilepsy patients using Sanger sequencing." (PMID 39361439, 2024). "In conclusion, we report two novel heterozygous variants in the HCN3 identified in two unrelated patients with epilepsy." (PMID 39361439, 2024). "Our study provides functional evidence supporting the pathogenicity of these variants, thereby underscoring the potential causal role of HCN3 in epilepsy." (PMID 39361439, 2024). "In this study, we identified three variants in the HCN3 in individuals with epilepsy who responded well to treatment." (PMID 39361439, 2024). "Non-synonymous variants of HCN3 have been described in humans and are associated with epilepsy and SUDEP." (PMID 35663267, 2022). "Due to the fact that HCN3 channelopathy is related to epilepsy and SUDEP, future studies can explore its association with the occurrence of epilepsy." (PMID 35663267, 2022). "Due to the fact that HCN3 channelopathy is related to epilepsy and death, future studies may explore its association with the occurrence of epilepsy in living patients." (PMID 35663267, 2022). "However, the association of HCN3 variants with epilepsy has been scarcely explored." (PMID 39361439, 2024). "Comprehensive in vitro functional assays demonstrated that these variants significantly affect channel function and stability, suggesting a potential role for HCN3 in the development of epilepsy." (PMID 39361439, 2024). "After identifying HCN3 variants, we planned to conduct further studies, including WES, to explore other genetic factors contributing to epilepsy in our cohort." (PMID 39361439, 2024). "Our study was initiated in 2014, following the discovery of HCN1's role in epilepsy, which sparked our interest in investigating the involvement of HCN3 in epilepsy due to its similarities to HCN channel subtypes." (PMID 39361439, 2024). "Pathogenic variants of HCN1, HCN2, HCN3, and HCN4 have been reported to be associated with epilepsy in 74 cases, and they have diverse phenotypes." (PMID 35663267, 2022). "We identified pathogenic variants of HCN1 (n = 24), HCN2 (n = 8), HCN3 (n = 2), and HCN4 (n = 6) that were associated with epilepsy in 74 cases (43 HCN1, 20 HCN2, 2 HCN3, and 9 HCN4)." (PMID 35663267, 2022). "This study suggests that HCN3 may be a novel candidate gene in the pathogenesis of epilepsy, but additional cases, segregation evidence, and in vivo validation are required." (PMID 41603014, 2026). "Interestingly, the blockage of HCN1-mediated Ih current in the pyramidal, cortical, and thalamic neurons contributes to epilepsy, whereas blockers of HCN3- and HCN4-mediated currents suppress seizures." (PMID 35663267, 2022).
epilepsy (continued). "A study showed that HCN3-deficient mice exhibit compromised processing of contextual information, but this study only explored the role of HCN3 channel in the regulation of circadian rhythm and behavior, rather than epilepsy." (PMID 35663267, 2022). "To date, there is no animal model for epilepsy specifically related to HCN3." (PMID 39361439, 2024).
Anxiety (2 papers, 2017 to 2026). Intense feelings of nervousness, tension, or panic often arise in response to interpersonal stresses. "In line with this interpretation in the dark-light test, another test for exploration-based anxiety, HCN3−/− and wild type mice behaved similar." (PMID 29375299, 2017).
migraine (2 papers, 2019 to 2022). "The in-silico analysis showed that the target genes, i.e., HCN3, NAV3, GPR158 for miR-34a-5p and MTPN for miR-375, are involved in trigeminal pain circuit of migraine." (PMID 35682695, 2022). "In particular, HCN3 belong to hyperpolarization-activated potassium channels family proteins involved in trigeminal ganglion neuron activation, while NAV3 and GPR158 are emerging in migraine." (PMID 31252698, 2019).
neuroblastoma (2 papers, 2016 to 2024). Neuroblastoma (NB) is the most common solid, extracranial childhood tumor. "In this context, the lncRNAs MEG3, HCN3, and linc01105 have been identified as relevant in neuroblastoma tumorigenesis: their expression levels are associated with International Neuroblastoma Staging System (INSS) staging." (PMID 38891878, 2024). "Low and high expression levels of linc01105 and HCN3 are found in low- and high-stage neuroblastoma, respectively." (PMID 38891878, 2024). "HCN3 and linc01105 exhibited the higher expression (P < 0.05; P < 0.01, respectively) in neuroblastoma tissue, whereas MEG3 displayed the lower expression (P < 0.01)." (PMID 27824082, 2016). "We identified MEG3, HCN3 and linc01105 as lncRNAs that are relevant to neuroblastoma." (PMID 27824082, 2016). "The expressions of MEG3, HCN3 and linc01105 were all correlated negatively with the INSS neuroblastoma stage; low and high expressions of these genes were associated with early and late tumor stages, respectively." (PMID 27824082, 2016). "Consistent with the microarray results, the qRT-PCR analysis revealed that the expression levels of HCN3 (P < 0.05) and linc01105 (P < 0.01) were higher, whereas MEG3 expression was lower (P < 0.01), in neuroblastoma tissue compared to para-tumor tissue." (PMID 27824082, 2016).
bladder cancer (1 paper, 2022). "Then, 9 target genes that were differentially expressed between bladder cancer and normal samples were screened (FDR < 0.05), in which upregulated expression of RHBG, PAQR6, CLK2, KRTCAP2, FLAD1, HCN3 were correlated with bad survival of patients with bladder cancer." (PMID 36186809, 2022).
cognitive decline (1 paper, 2024). "In parallel, western blots of the hippocampus of presymptomatic mice (4 months old) were probed with antibodies to HCN1, HCN2, and HCN3 to monitor whether changes in the expression of HCN channels occur before overt cognitive decline in Tau35 mice." (PMID 38994745, 2024).
heart failure (1 paper, 2020). Inability of the heart to pump blood at an adequate rate to meet tissue metabolic requirements. "High expression of Hcn2 and Hcn3 are associated to cause sinoatrial node dysfunction ultimately leading to heart failure." (PMID 32673370, 2020).
leprosy (1 paper, 2021). Leprosy is a chronic infectious disease affecting primarily the skin and peripheral nervous system. "Moreover, variants under selection in the HCN3 are in LD with the SNP associated with leprosy susceptibility–rs1052176 –which is highlighted as an eQTL for PKLR and HCN3 genes by GTEx." (PMID 34449765, 2021).
liver steatosis (1 paper, 2025). "In thymectomized mice, we observed an upregulation of novel genes that have demonstrated to either be causal (Mogat1, Pklr) or associated with liver steatosis (Serpina7, and Hcn3)." (PMID 41034932, 2025).
malaria (1 paper, 2021). Malaria is a serious and sometimes fatal disease caused by a parasite that commonly infects a certain type of mosquito which feeds on humans. "Evidence for association between the HCN3 variants and malaria in Africa have been raised by Machado and colleagues (2010), who observed a conserved haplotype and high heterozygosity at this gene associated with an uncomplicated malaria group in Angola." (PMID 34449765, 2021). "Consistently, variants at HCN3 have been associated with RBC deficiency and the variant rs1052176 has been linked with malaria." (PMID 34449765, 2021).
peripheral nerve injury (1 paper, 2026). Injury to a peripheral nerve. "In particular, Hcn3−/− mice showed normal acute thresholds to heat or mechanical stimuli, unaltered inflammatory pain, normal mechanical allodynia, and thermal hyperalgesia after peripheral nerve injury, but reduced responses to a pinprick after peripheral nerve injury." (PMID 41601547, 2026).
pituitary tumor (1 paper, 2022). A benign or malignant neoplasm affecting the pituitary gland. "HCN2, HCN3, or mixed HCN2 + HCN3 channels were reported previously to be distributed in pituitary tumor (GH3) cells." (PMID 35806190, 2022).
steatosis (1 paper, 2025). Increased lipid within the cytoplasm of cells. "Thymectomy also resulted in upregulation of Serpina7 and Hcn3 which are highly upregulated in various models and tissues of diet induced steatosis, however the exact role of these genes in hepatic dysfunction is still unclear." (PMID 41034932, 2025).
Stroke (1 paper, 2026). Sudden impairment of blood flow to a part of the brain due to occlusion or rupture of an artery to the brain. "Using this light-touch stroke assay, we observed a significantly reduced number of unpleasant reactions in Hcn3−/− mice." (PMID 41601547, 2026).
tauopathy (1 paper, 2024). Neurodegenerative disorders involving deposition of abnormal tau protein isoforms (tau proteins) in neurons and glial cells in the brain. "Progressive increases in HCN1 and HCN3 ion channel expression are accompanied by an array of dendritic, synaptic, and ultrastructural changes as well as the development of tau pathology in Tau35 mice, with decreases in dendritic branching observed only during advanced tauopathy." (PMID 38994745, 2024).
trigeminal neuralgia (1 paper, 2019). Trigeminal neuralgia is a nerve disorder that causes a stabbing or electric-shock-like pain in parts of the face. "In this view gene such HCN3, NV3, and GPR158were found in DIANA-TOOLS database associated in trigeminal neuralgia and targets of hsa-miR-34a-5p." (PMID 31252698, 2019).
triple-negative breast carcinoma (1 paper, 2024). An invasive breast carcinoma which is negative for expression of estrogen receptor (ER), progesterone receptor (PR), and human epidermal growth factor receptor 2 (HER2). "Furthermore, overexpression of HCN3 is implicated in the development and progression of triple-negative breast cancer." (PMID 38636662, 2024).
tumor (4 papers, 2016 to 2026). "We also validated significantly upregulated expression of ER‐stress markers GRP78, ATF4, CHOP and apoptosis marker BIP, BIM, cleaved caspase 3 in the tumour xenografts with HCN2 or HCN3 knockdown." (PMID 34841695, 2021). "Similarly, depletion of HCN2 or HCN3 by shRNA could significantly reduce the growth rate of the tumours in vivo." (PMID 34841695, 2021). "Consistently in the xenograft model, a low dose of Ivabradine (1 mg/kg) or paclitaxel (2 mg/kg) alone, given twice weekly, did not affect tumour volume or did not affect the expression of HCN2 and HCN3." (PMID 34841695, 2021).
cancer (2 papers, 2021 to 2026). A tumor composed of atypical neoplastic, often pleomorphic cells that invade other tissues. "Therefore, the future effort can be made to develop a drug that recognizes explicitly HCN2 and HCN3 only, which would be expected to be more cancer‐specific than Ivabradine." (PMID 34841695, 2021).
HCN3 also shares sentences with these, for which no sentence is quoted: epileptic syndrome (2 papers); atrial fibrillation (1); breast tumour (1); channelopathy (1); colorectal cancer (1); Hirschsprung disease (1); renal carcinoma (1); sleep disorder (1); tuberculosis (1).